IL6 (interleukin 6)
Diseases named in the same sentence as IL6 in open-access papers (continued):
Sharing a sentence is not in itself a finding about the gene and the disease.
anemia (continued). "Increased levels of TNF, IL-6 and IL-8 as well as decreased IL-10:TNF or TGF-β1:TNF ratios are associated with anemia." (PMID 30930847, 2019). "Together, those studies illustrate the complex relationship between hepcidin and IL-6 in the development of anaemia in MM." (PMID 31683939, 2019). "In a double-blind, placebo-controlled Phase II study, anti-IL-6 monoclonal antibody (siltuximab) was assessed in patients with low- and intermediate-1-risk MDS who require regularly transfusions for MDS anemia." (PMID 29924032, 2018). "The IL-6/hepcidin signalling pathway plays a major role in the development of anaemia in an inflammatory condition." (PMID 29482530, 2018). "When adjusted for maternal anemia (as a proxy for maternal nutrition), TNFα and IL6 remained significant predictors (p < 0.05)." (PMID 30705878, 2018). "Hepcidin production in the liver increases in response to cytokines, such as interleukin 6 (IL-6), whereas both low plasma iron levels and anemia suppress hepcidin." (PMID 29717382, 2018). "When these models were adjusted for maternal anemia, only TNFα and IL6 remained significant predictors of WAZ at final visit (p < 0.05)." (PMID 30705878, 2018). "High serum IL-6 related to anemia (P < 0.01), high CRP levels (P = 0.02), severe fatigue (P = 0.02) and hepatic metastasis (P < 0.01)." (PMID 28177923, 2017). "Many HLH-related and MCMV-induced cytokines are known to suppress hematopoiesis, amongst which IL-1β, IFN-γ and TNF-α, whereas IL-6 has the potency to specifically induce anemia." (PMID 29258535, 2017). "Several studies have also demonstrated that high levels of IL-6 contribute to the clinical development of anemia and elevated C-reactive protein (CRP) levels." (PMID 28851899, 2017). "The most significant results were associations between cognitive dysfunctions and genetic polymorphisms, including APOE-4 and COMT-Val; increased plasma levels of the pro-inflammatory cytokine, IL-6; anemia; and hemoglobin levels during chemotherapy." (PMID 28377717, 2017). "Iron loading, inflammation, and interleukin-6 (IL-6) increase the production of hepcidin, determining anemia, increased erythropoietin, or hypoxia, which stimulates bone marrow erythropoiesis." (PMID 28216608, 2017). "Excess production of IL-6 contributes to inducing hepcidin production and thrombocytosis, which lead to anemia common in active RA." (PMID 29104606, 2017). "The pathophysiology of anemia during infections is multifactorial, resulting from the effects of inflammatory cytokines, such as IL-6 and possibly other cytokines involved in host defense and leading to hepcidin-induced hypoferremia." (PMID 29258550, 2017). "Either liver-specific STAT3 knockout or IL-6 knockout mice demonstrate attenuated hepcidin induction or anemia in response to inflammatory stimuli." (PMID 29147463, 2017). "Inflammatory markers associated with greater severity of anaemia in both patient groups included increasing CRP, IL-1β and IL-6 concentrations." (PMID 26792471, 2016). "Hepcidin synthesis by hepatocytes is suppressed by erythropoietic activity while systemic inflammatory diseases increase hepcidin synthesis through IL-6 and other mediators, leading to anemia of inflammation or anemia of chronic diseases." (PMID 27635343, 2016). "IL-6 seems to play several roles in the anemia of cancer by acting at the level of the bone marrow by inducing ineffective erythropoiesis and at the level of the reticuloendothelial system by changing iron diversion by up-regulating hepcidin." (PMID 27068103, 2016). "We demonstrated that inhibition of IL-6 signaling by MR16-1 treatment resulted in not only the reduction of elevated hepcidin levels which led to the improvement of anemia status but also the systemic amelioration of disease symptoms." (PMID 27068103, 2016).
anemia (continued). "LC-06-JCK–bearing mice developed anemia according to the production of human IL-6 from xenografts, with decreased values of hemoglobin, hematocrit, and mean corpuscular volume (MCV) compared to non–tumor-bearing (NTB) mice." (PMID 27068103, 2016). "Because IL-6 is thought to be an important cause of the anemia of inflammation by inducing hepcidin expression, we used SAA levels as an indicator of IL-6 activity." (PMID 27068103, 2016). "There is direct evidence that recombinant human IL-6 (rhIL-6) treatment as an antitumor immunotherapy induces anemia in cancer patients and that this anemia is reversible after the cessation of rhIL-6 treatment." (PMID 27068103, 2016). "We previously established an LC-06-JCK mouse model of anemia that showed high levels of IL-6 and low levels of Hb." (PMID 27068103, 2016). "Typically there are also laboratory abnormalities: hypergammaglobulinemia, elevated inflammatory parameters, anemia, thrombocytosis, leucopenia, low serum albumin level, and, sometimes, elevated interleukin-6 (IL-6)." (PMID 25737793, 2015). "Anemia in ESRD is regarded to have traits of ACD showing increased IL-6 and hepcidin concentrations, so that iron is rendered scarce for erythropoiesis." (PMID 26445018, 2015). "Systemic inflammation is a well-known cause of anemia, mediated by inflammatory cytokines such as tumor necrosis factor alpha (TNF-α), interleukin-1 (IL-1), interleukin-6 (IL-6), and interferon-γ (IFN-γ)." (PMID 26024473, 2015). "Over-expression of hepicidin induced by interleukin-6 changes the availability of iron and leas to anaemia in CKD patients." (PMID 25793395, 2015). "In monkey NOX-H94 prevented the onset of anemia induced by IL6, in human volunteers, it increased indices of iron availability and was safe and well tolerated, it also delayed the onset of hypoferremia in volunteers treated with LPS." (PMID 24808863, 2014). "It implies the central role of IL-6 in anemia of RA patients and suggests that TCZ would be a good option for RA patients with anemia." (PMID 24878740, 2014). "This, so named ZIGI mouse model, is characterized by high IL6 and hepcidin, increase in spleen iron content with a decrease of liver ferroportin and anemia 5 days after Zymosan injection." (PMID 24808863, 2014). "On the other hand, some cytokines, such as interleukin-6 (IL-6), have been demonstrated to induce anemia." (PMID 25207808, 2014). "The IL6-KO and hepcidin-KO mice showed a milder anemia and a faster recovery confirming the role of inflammation and of hepcidin in the development of anemia in this model." (PMID 24808863, 2014). "A positive correlation was found between serum hepcidin and IL-6 levels (r = 0.546, p = 0.023) in 17 patients with Crohn’s disease and anemia from this disease." (PMID 24576354, 2014). "One important question is why IL6 stimulation reduces iron blood levels and induces anemia of inflammation even though the homeostasis loop should effectively buffer IL6-induced perturbations in hepcidin expression." (PMID 24391488, 2014). "The finding that hepcidin is upregulated by the inflammatory cytokine IL6 contributed to explain the anemia of chronic diseases (ACD) alias AI." (PMID 24808863, 2014). "The clinical signs (febrile responses, thrombocytopenia and anemia) associated with acute EIA are mediated by pro-inflammatory cytokines, such as TNFα, IL-6, and TGFβ." (PMID 25390683, 2014). "IL-6 inhibition by TCZ was effective in correcting anemia in Castleman's disease which is characterized by the overproduction of IL-6 from lymph nodes." (PMID 24878740, 2014). "The ZIP14 transporter in hepatocytes accomplishes the systemic removal of zinc and it is up-regulated by the acute phase cytokine interleukin-6, further stating the central role of interleukin-6 in promoting anemia of inflammation." (PMID 23519291, 2013).
anemia (continued). "Clinical trials in non-small cell lung cancer (NSCLC) reveal that IL-6 targeted therapy relieves NSCLC-related anemia and cachexia, although other clinical effects require further study." (PMID 24260500, 2013). "Nevertheless, JTT prevented deterioration of patients' conditions, such as anemia, lymphopenia, hypoalbuminemia, plasma IL-6 elevation, and reduction of performance status, which are frequently observed in advanced cancers." (PMID 23840274, 2013). "In our study, we noticed that in the anemia group, with the increase of IL-6 level, the proliferation of the BMSC was obviously impeded." (PMID 23853724, 2013). "The best way to type anaemia of chronic inflammation is to measure serum hepcidin which is an iron-regulatory hormone that is produced in response to inflammatory cytokine IL-6 following inflammation." (PMID 24194926, 2013). "Acute anemia or lipopolysaccharide (LPS) challenge alone triggered an increase of circulating levels of the inflammatory markers IL-6 and keratinocyte-derived chemokine (CXCL1/KC)." (PMID 22919395, 2012). "Participants with anemia of chronic diseases had significantly higher IL-6 and C-reactive protein (CRP) levels, while those with unexplained anemia had significantly lower CRP than nonanemic controls." (PMID 23091709, 2012). "We observed that the combination of anemia and LPS administration resulted in higher plasma levels of the inflammatory markers IL-6 and CXCL1/KC than did either challenge alone." (PMID 22919395, 2012). "IL-6 induces acute-phase proteins and contributes to the systemic manifestations of RA though hepcidin production (anemia) and acts potently in changing lipid concentrations (hypolipidemia)." (PMID 22046525, 2011). "In conclusion, our study demonstrates that patients requiring high-dose ESA for treatment of CKD-related anemia are more likely to have increased levels of the pro-inflammatory biomarkers IL-6 and CRP." (PMID 22152013, 2011). "Anticytokine therapies such as anti-IL-6 antibody were shown to suppress hepcidin production and improve anemia." (PMID 20066043, 2010). "Aging is also associated with increased inflammation and a mild rise in inflammatory markers, including IL-6, and elderly patients with anemia have been found to have higher levels of inflammatory markers than elderly patients without anemia." (PMID 20368776, 2010). "Il6 has been proposed as a key link between inflammation and anaemia via its activation of hepcidin (Hamp), which acts as a negative regulator of intestinal iron absorption and macrophage iron release." (PMID 19365556, 2009). "The constitutional symptoms, such as fever, weight loss, anemia, arthralgias and rash, rely on an immunologic response with an increase of CRP, IL-6 and γ-globulin due to bleeding and degeneration within the mass and releasing tumor fragments." (PMID 19818150, 2009). "The inverse correlation of hemoglobin with AGP, CRP, and IL-6 suggests the role of proinflammatory cytokines and inflammation in the anemia of chronic infection." (PMID 15588289, 2004). "A significant increase in plasma 25OHD (40.1 ± 17.8, p < 0.001) and in Hb (12.4 ± 2.0, p = 0.01) was observed at 3 months with a decrease in the prevalence of anemia (n = 17, p = 0.015) and of Interleukin 6 in plasma levels [IL-6, 10.7 (5.8-23.3) vs. 6.5 (4.1-11.8), p = 0.016]." (PMID 42201059, 2026). "Nonetheless, IL-6 blockade remains an important option for patients who cannot tolerate other therapies or in whom IL-6–mediated symptoms (e.g., systemic inflammation, anemia) are prominent." (PMID 40791602, 2025). "Systemic and non-specific symptoms are thought to arise from interleukin-6 (IL-6)–mediated inflammatory responses induced by the tumor, including fever, fatigue, weight loss, arthralgia, myalgia, and anemia." (PMID 41440527, 2025). "Additionally, elevated IL6 levels stimulate ROS production, which affects kidney function and reduces erythropoietin production, contributing to anemia." (PMID 40427188, 2025).
anemia (continued). "One hypothesis involves the pro-inflammatory state associated with heart failure, in which elevated levels of cytokines such as interleukin-6 contribute to anemia of chronic inflammation." (PMID 41451092, 2025). "The role of IL-6 in the pathophysiology of anemia in chronic diseases is significant." (PMID 40046064, 2025). "This raises the possibility of comparable adaptation despite the disruption of the homeostatic mechanisms that integrate central and peripheral control of thyroid activity, possibly under the influence of IL-6 or anaemia, or other systemic mediators of severe or prolonged illness." (PMID 41286140, 2025). "PCa metastasis is directly linked to elevated IL-6 and TNF-α levels, which in turn drive an upsurge in CRP and FIB levels in the body, prevent iron from being absorbed as the building block of hemoglobin, and worsen anemia." (PMID 41142623, 2025). "In addition, an increased interleukin-6 in the patients with malignancy elevates hepatic synthesis of hepcidin, participating in anemia of chronic diseases." (PMID 40821323, 2025). "In their study, it was demonstrated that caffeine attenuates hepcidin expression through the suppression of inflammation and the modulation of the IL-6/STAT3 signaling pathway, thereby presenting a compelling potential intervention for the management of anemia associated with inflammation." (PMID 40299525, 2025). "By decreasing HB’s ability to absorb iron through the upregulation of hepcidin, IL-6 may exacerbate anemia." (PMID 41142623, 2025). "Indeed, TNF-α, IL-6, and IL-1 are thought to contribute to RA-anemia development by modulating iron metabolism and suppressing bone marrow erythropoiesis, particularly by affecting the serum hepcidin level." (PMID 40648921, 2025). "It is known that IL-6 increases the expression of hepcidin, which regulates iron recycling and absorption, as it blocks iron release from body stores by downregulating ferroportin expression, leading to anemia." (PMID 39684440, 2024). "Additionally, IL-6 and other inflammatory cytokines induce the expression of hepcidin by the pathway JAK2/STAT3, causing anemia of inflammation." (PMID 38396414, 2024). "With sustained elevation of IL-6, patients may experience hypoalbuminemia, hyponatremia, and anemia." (PMID 39220153, 2024). "IL6 suppresses the differentiation of normal HSCs, leading to cytopenia and anemia." (PMID 39769050, 2024). "Targeting specific inflammatory cytokines, such as IL-6 or TNF-alpha, may improve both RA symptoms and associated anemia." (PMID 39588439, 2024). "Moreover, prolonged IL-6 activation induces anemia and elevates plasma levels of CRP and immunoglobulins, potentially affecting the intestinal microbiota." (PMID 39703501, 2024). "The relationship between IL-6 and AEs was evaluated at high and low cutoff values for IL-6 and OS, and the results showed that the incidences of fatigue, pruritus/rash, anemia, pain, and hypothyroidism in the lower cutoff value group were lower than those in the higher cutoff value group (p > 0.05)." (PMID 38769368, 2024). "However, previous translational studies have found elevated IL-6 involved in inflammation-induced anemia due to suppression of erythropoiesis." (PMID 38647741, 2024). "However, the pathophysiology of anemia of inflammation has large overlap within these different syndromes and IL-6 inhibitors have similar results on slowing onset of anemia." (PMID 38594746, 2024). "In addition, malaria status predicted TNF‐α, IFN‐ɣ, IL‐1β, IL‐6, GM‐CSF and IL‐10 levels, whiles anemia severity predicted only IL‐3, IL‐10 and TGF‐β levels." (PMID 39240033, 2024). "Moreover, anemia observed with chronic inflammation involves increased hepcidin expression due to elevated IL‐6, and cases of iron ineffectiveness in such inflammatory anemia have been reported." (PMID 39114446, 2024).
anemia (continued). "Among them, two cases were found to have anemia and elevated inflammatory indicators by laboratory examination, which may be related to the production of cytokines such as IL-2 and IL-6 by tumor cells." (PMID 39144665, 2024). "However, the correlation between protection from anemia as a measure of disease severity and IL-6 levels suggests that IL-6 is a measurable parameter to optimize agonist, dose and formulation." (PMID 39208226, 2024). "In addition, IL-6 levels in the severe malarial anemia group were significantly higher than in the uncomplicated malaria group [36.03 (15.36–97.86) pg/ml vs. 5.99 (3.50–93.98) pg/ml; p = 0.042]." (PMID 36787308, 2023). "Moreover, cancer treatment with recombinant human IL-6 has been found to induced anemia and hypoferremia, and a cancer-induced anemia mouse model has been established by inoculation with IL-6-producing human or mouse tumor cell lines." (PMID 37208766, 2023). "Also, IL-6 induces hepcidin production, which has a role in iron homeostasis and anemia and is a factor in heart failure." (PMID 37764213, 2023). "Another limitation is due to the lack of testing materials, we were unable to assess iron parameters like serum iron level and ferritin level (we have not investigated iron deficiency anemia) and inflammatory cytokines like IL-6 and TNFα." (PMID 37344827, 2023). "Combined ICIs and IL-6 inhibition may therefore be effective in reducing anemia, limiting immune-related toxicity and enhancing anti-tumor immunity." (PMID 37208766, 2023). "A clinical trial of anti-IL-6 showed remarkable efficacy in anemia of CKD." (PMID 35905974, 2023). "The inflammatory response to an infection, characterized by the secretion of interleukin-6 (IL-6) in significant amounts, could be a primary factor contributing to anemia." (PMID 38109177, 2023). "Thus, TNFα, IL-1β, IL-6 and IFN-γ seem to be responsible for impaired EPO synthesis in the development of anemia associated with inflammation." (PMID 37240288, 2023). "Moreover, only IL-10 and IL-6 levels were significantly higher in children with severe malarial anemia compared to children with uncomplicated malaria who had significantly lower IL-10 levels than children with moderate malarial anemia." (PMID 36787308, 2023). "In addition, we observed higher baseline serum IL-6 levels in patients who evolved with long-term anemia." (PMID 37390095, 2023). "Deranged hematological and biochemical laboratory findings in the form of anemia, neutrophilia, lymphopenia, raised postprandial blood sugar (PPBS), HbA1c, serum creatinine, c-reactive protein (CRP), pro-calcitonin, D-Dimer, and IL-6 has been associated with COVID-19 disease." (PMID 37284389, 2023). "The important role of inflammation in the pathogenesis of CKD anemia was demonstrated by the beneficial effects of anti-IL-6 therapy on anemia in hemodialysis-dependent patients, several of whom were able to discontinue erythropoiesis-stimulating agents altogether." (PMID 35905974, 2023). "In addition, TB patients with mild disease displayed immune polarization towards mixed Th1/Th2 responses, while IL-6, IL-8, and the IL-20 subfamily of cytokines were more predominant in mod-sev TB disease and anemia of TB." (PMID 38162636, 2023). "Moreover, IL6 is capable of correcting anemia in combination with IL3, making rapid activation of platelets by thrombin and platelet activating factor, and exhibiting a procoagulant effect on ameliorating bleeding propensity." (PMID 36297316, 2022). "However, we found statistically significant differences in IL-6 concentrations between males with anaemia since hospital admission and comorbidities and those without comorbidities." (PMID 36612220, 2022). "Furthermore, similar findings were noted in a preclinical study: namely, IL-6 − induced pSTAT3 was reduced in HepG2 cells and a rat model of anemia of chronic disease after treatment with momelotinib." (PMID 35045875, 2022).